STAT3 (signal transducer and activator of transcription 3)
Diseases named in the same sentence as STAT3 in open-access papers (continued):
Sharing a sentence is not in itself a finding about the gene and the disease.
glioma (continued). "Both glioma cell lines (U87MG and its STAT3 knockout variant U87MG-STAT3KO) were next implanted into the Foxn1-nude mice and for 28 days the tumor growth was monitored with simultaneous administration (from 15th day after implantation) of TMZ at 0.9 mg/kg concentration." (PMID 38654280, 2024). "In recent years, there has been a surge in research on STAT3 and pyroptosis, suggesting that STAT3 may constitute a component of the signaling pathway regulating glioma pyroptosis." (PMID 39069522, 2024). "Importantly, murine CMV infection led to increased phosphorylated STAT3 levels in neural stem cells, suggesting a potential mechanism for glioma modulation." (PMID 39516641, 2024). "This immunosuppressive effect of H2O2 on T cells, mediated by CYB561D2 and STAT3, could ultimately lead to T cell apoptosis and contribute to the immunosuppressive environment in gliomas." (PMID 37469162, 2024). "The possible mechanism by which STEAP3 promotes glioma progression may be through the activation of TfR and the downstream ferritin-STAT3 pathway." (PMID 37009153, 2023). "The anti-VEGF therapy also reported that the overexpression of STAT3 in glioma patients and STAT3 inhibitors could be therefore used to enhance the anticancer treatment." (PMID 38201528, 2023). "Targeting STAT3 sensitizes glioma cells to anti-EGFR (Iressa/gefitinib) and alkylating agents." (PMID 36900355, 2023). "Furthermore, they found that the knockdown of MFG-E8 inhibits glioma cell growth via the ITGB3/FAK/ERK or ITGB3/STAT3/cyclin D3 signaling pathways and suppresses M2 polarization." (PMID 37759870, 2023). "Collectively, our results confirmed that IGF2BP3/circGNB1/miR-515-5p/miR-582-3p/XPR1 axis could promote tumorigenesis and malignant progression of glioma via IL6/JAK2/STAT3 signaling pathway." (PMID 37407973, 2023). "JAK2/STAT3 and Notch1 signaling activation.Glioma stem marker expression." (PMID 37762011, 2023). "STAT3 is, therefore, an emerging target of let-7 in glioma and, fitting with its broad biological functions, may be in part responsible for the broad glioma suppressive functions of let-7." (PMID 37370851, 2023). "Notably, the interaction of epidermal growth factor receptors (EGFR) with signal transducer and activator of transcription 3 (STAT3) or the constitutive activation of EGFR variant III/STAT3 pathway enhances the COX2 signaling and favors glioma angiogenesis." (PMID 37071295, 2023). "Subsequently, astrocyte-derived IL-6 acted on glioma cells, leading to further STAT3 activation." (PMID 36923251, 2023). "In addition, paeoniflorin induces ferroptosis in human glioma cells by increasing NEDD4L-dependent STAT3 ubiquitination." (PMID 38027016, 2023). "It was shown that there was a cross-activation of IL6/STAT3 between glioma cells and astrocytes." (PMID 36923251, 2023). "Knockdown or overexpression of ZDHHC15 in glioma could regulate tumor cell proliferation and migration by targeting the STAT3 signaling pathway." (PMID 37161425, 2023). "We then investigate whether STAT3 present in nuclear lysate of glioma cells could bind to the − 328 to − 336 and − 378 to − 386 at the FOSL1 promoter by performing ChIP-qPCR." (PMID 37642779, 2023). "Moreover, not only STAT3 but also STAT1 can control FOXM1 expression in different glioma cell lines (U87, A172, U251, and T98), influencing other signaling pathways implicated in inflammation, such as NF-κB." (PMID 37821870, 2023). "Similarly, αVβ5 integrins on M2-macrophages secreted TGF-β and activated the Src/Stat3 signaling pathway, which promoted the maintenance of glioma stem cells (GSCs) and glioma growth." (PMID 37047140, 2023). "Additionally, univariate and multivariate regression analysis and ROC curve analysis indicated that STAT3 can be used as an independent prognostic factor of glioma with a certain degree of robustness." (PMID 37724127, 2023). "Glioma cell-derived IL-6 activated STAT3, which upregulated IL-6 expression in astrocytes." (PMID 36923251, 2023).
glioma (continued). "CRNDE could promote the malignant progression of glioma by attenuating the miR-384/PIWIL4/STAT3 axis." (PMID 37152037, 2023). "TMSB10 may involve glioma immune regulation progression by promoting PD-L1 expression levels via activating STAT3 signaling pathway." (PMID 37275863, 2023). "The pathways enrichment analysis indicated TMSB10 was positively associated with IL6/JAK/STAT3 signaling pathway, and we also found TMSB10 was positively associated with IL-6 in patients with primary/recurrent glioma (grade III: r=0.46, P<0.001, grade IV: r=0.317, P=0.003)." (PMID 37275863, 2023). "Phosphorylated STAT3 also has significant implications for guiding glioma treatment." (PMID 36923251, 2023). "Conversely, overexpression of ZDHHC15 in glioma cell lines resulted in increased p-STAT3 levels." (PMID 37161425, 2023). "IL-6 is highly expressed in human glioma specimens and cell lines, and activates the transcription of multiple tumor suppressor genes through STAT3 (signal transducer and activator of transcription 3) signaling pathway to promote the proliferation and inhibit apoptosis of U251 and A172 cell lines." (PMID 38259287, 2023). "In addition, the activation of JAK2/STAT3 pathway regulates malignant behaviors of glioma cells, including the proliferation and invasion of glioma cells." (PMID 36814203, 2023). "This demonstrated the aberrant activation of STAT3 in glioma stem cells." (PMID 36923251, 2023). "Moreover, STAT3 was hyperactivated in glioma and excessive activation of STAT3 promoted gliomagenesis, cell survival, proliferation, migration, angiogenesis, and other biological effects." (PMID 37161425, 2023). "STAT3 expression varies in patients with different glioma grades." (PMID 36923251, 2023). "Ubiquitination of STAT3 by NEDD4L induces its downregulation in glioma cells." (PMID 38027016, 2023). "Moreover, TANK indirectly phosphorylates the transcription factor STAT3 to increase the release of interleukin-6 (IL-6) and ultimately accelerate the progression of glioma in terms of enhanced angiogenesis and proliferation." (PMID 37215097, 2023). "Studies have shown that IL-6 can promote the migration of glioma cells, and cucuritin-1, a specific inhibitor of STAT3, can inhibit this promoting effect of IL-6, suggesting that IL-6 may regulate the invasion of glioma through JAK/STAT pathway." (PMID 38259287, 2023). "We previously reported that TRPM7 regulates glioma cells’ stemness through STAT3." (PMID 37642779, 2023). "To further characterize this finding, we built on results from several recent reports which have underlined the role of macrophages to induce MES-like cell-state by implicating macrophage-derived oncostatin M (OSM) with its receptors and activating STAT3 signaling in glioma." (PMID 35144680, 2022). "In glioblastoma, for instance, IL-6 has been reported to induce NFκB, resulting in STAT3 activation and greater tumor aggressiveness, while inhibition of IL-6/STAT3 and NFκB decreases glioma growth, and these results support an impact of inflammation on brain tumor development." (PMID 36232813, 2022). "Fluorescence in situ hybridization (FISH) and immunohistochemical staining showed that LINC00346 was highly expressed in high-grade glioma, while type 2 macrophages key transcription factor STAT3 and surface marker CD204 were also highly expressed simultaneously." (PMID 36311792, 2022). "Next, we validated the correlation of KAT6B and STAT3 in the regulation of glioma cells." (PMID 35432536, 2022). "The KAT6B was able to enrich on the promoter of STAT3 in glioma cells." (PMID 35432536, 2022).
glioma (continued). "Therefore, we concluded that KAT6B contributes to glioma progression by repressing ferroptosis via epigenetically inducing STAT3." (PMID 35432536, 2022). "Since over-expression of STAT3 in glioma cells can induce resistance to the effects of paeoniflorin on cellular apoptosis and proliferation, these results indicate that STAT3 may be a key protein in the regulation of glioma cells by paeoniflorin." (PMID 36046834, 2022). "Therefore, this project aims to study the effect and mechanism of PF/NEDD4L/STAT3 on the proliferation of glioma." (PMID 36618071, 2022). "When STAT3 is silenced, migration of cancer stem cells towards macrophage secreted factors appears to be reduced; in fact, co-habitation of glioma stem cells and macrophages appears to result in bi-directional signalling that alters the phenotypes of both cell types." (PMID 36555253, 2022). "STAT3 and 5, which are involved in promoting cell cycle progression, cell transformation, and preventing apoptosis, have been found in abundance in gliomas, and there is a lot of evidence that their aberrant activation contributes to glioma development." (PMID 36497459, 2022). "In order to investigate whether NEDD4L regulates glioma cell proliferation through manipulating STAT3, we generated STAT3-overexpressing U251 glioma cells, and the overexpression of STAT3 was validated by both qPCR and western blot." (PMID 36618071, 2022). "STAT3 (signal transducer and transcription activator 3) plays a critical role in the pathogenesis of gliomas, immune suppression, immune cell tolerance, the proliferation and migration of glioma cells, promoting angiogenesis, and the stemness maintenance of CSCs." (PMID 36231068, 2022). "STAT3 is persistently activated in nearly 70% of human cancers, especially in gliomas." (PMID 34992215, 2022). "We then carried out a coimmunoprecipitation (Co-IP) assay to determine whether STAT3 interacts with NEDD4L in glioma U251 cells." (PMID 36618071, 2022). "Herein, we describe a selection of oncogenic (GLI-1/2/3, E2F1–8, STAT3, and HIF-1/2) and tumor suppressor (NFI-A/B, TBXT, MYT1, and MYT1L) TFs that are deregulated in gliomas and are subsequently associated with tumor development, progression, and migratory potential." (PMID 35409080, 2022). "For the first time, we associated TMEM158 with glioma cell growth, migration, and invasion via EMT and STAT3 signaling, suggesting that it may represent a useful therapeutic target for GBMs." (PMID 34992215, 2022). "In addition, STAT3 has been suggested to participate in glioma cell progression by shaping the immune microenvironment." (PMID 36618071, 2022). "Meanwhile, STAT3 may be just one of the downstream factors of KAT6B-mediated glioma progression, and other mechanisms should be identified in future investigations." (PMID 35432536, 2022). "Meanwhile, STAT3, as a crucial transcription factor, plays crucial oncogene roles in glioma." (PMID 35432536, 2022). "HIF-1α combined with JAK1/2-STAT3 (Janus kinase 1/2-signal transducer and activator of transcription 3) axis could enhance the self-renewal of glioma stem-like cells." (PMID 35607406, 2022). "The correlation between the JAK2/STAT3 pathway and glioma is extremely high." (PMID 36065261, 2022). "Furthermore, resveratrol reduced hypoxia-induced phosphorylation of STAT3 and decreased p-STAT3 levels in human glioma cells." (PMID 35566016, 2022). "Importantly, TMEM158 downregulation inhibited glioma cell growth and decreased the expression of p-STAT3 and Ki-67 in vivo." (PMID 34992215, 2022). "STAT3 can also protect CSCs from the innate immune system, as inhibiting activated STAT3 can reverse the suppression of phagocytosis and the secretion of IL-10 in glioma CSCs (gCSCs)." (PMID 36557902, 2022). "LIN00520 can be upregulated by SP1 in NSCLC, TFAP4 in glioma, and STAT3 in BC." (PMID 35309319, 2022).
glioma (continued). "With the advances in understanding of the JAK/STAT3 signaling in gliomas, it is gradually accepted that STAT3 is the junction site of multiple signaling pathways, and therefore, targeting the STAT3 signaling pathway has emerged as a promising therapeutic strategy for numerous cancers." (PMID 35281458, 2022). "We also detected that STAT3-controlled genes were upregulated in glioma NS." (PMID 36231068, 2022). "Thus, we concluded that KAT6B contributes to glioma progression by repressing ferroptosis via epigenetically inducing STAT3." (PMID 35432536, 2022). "However, our previous study suggested that the ubiquitination level of STAT3 was elevated in PF-treated glioma cells." (PMID 36618071, 2022). "Elevated levels of STAT3 tyrosine phosphorylation have been detected in glioma specimens or cells, indicating activation of STAT3, and glioma patients with a high proportion of STAT3 phosphorylation-positive cells were found to have shorter survival than those with a low proportion." (PMID 35281458, 2022). "In glioma, inhibiting STAT3 activation by pharmacological or genetic means has been shown to reduce Olig2 levels, observations that may tie together lucanthone’s mechanism with the observed reduction in Olig2." (PMID 35494072, 2022). "In addition, Stat3, a gene involved in cell proliferation and invasion, is activated in multiple cancers, including glioma." (PMID 35572197, 2022). "Moreover, miR-21 downregulates human telomerase reverse transcriptase expression through its action on Stat3, inhibiting glioma cell growth." (PMID 35572197, 2022). "A STAT3-based gene signature also has been shown to stratify glioma patients for targeted therapy." (PMID 35562901, 2022). "SD-36 selectively degraded STAT3, including mutated STAT3 proteins over other STAT proteins, even though they share a conserved SH2 domain in various leukemia, lymphoma and glioma cell lines." (PMID 35844493, 2022). "Furthermore, our xenograft data demonstrated that PF can suppress glioma tumor growth by activating NEDD4L/STAT3/Nrf2/GPX4 signal axis which eventually triggers ferroptosis." (PMID 36618071, 2022). "Taken together, this study demonstrates that PF can function as an antitumor agent for glioma treatment by targeting NEDD4L-dependent STAT3 ubiquitination as well as by regulating the Nrf2/GPX4 signaling axis, which might trigger ferroptosis." (PMID 36618071, 2022). "STAT3 contributes to glioma progression by promoting FOXP1 transcription." (PMID 35432536, 2022). "Interestingly, STAT3 knockdown in GSCs and conventional glioma cell lines coincided with the phenotypes described with SOX9 silencing of reduced self-renewing in vitro and decreased tumorigenic activity in vivo." (PMID 35562901, 2022). "In addition, transcription factors are also involved in the regulation of LINC00520, including SP1 in NSCLC, TFAP4 in glioma, and STAT3 in BC." (PMID 35309319, 2022). "Moreover, LBX2-AS1 depletoin not only downregulated LIF and p-STAT3 in glioma cells, but also affected the protein levels of N-cadherin, E-cadherin and Vimentin." (PMID 34729101, 2021). "This STAT3/TRIM24/ID1 axis mediates glioma stem cell proliferation and self-renewal." (PMID 33810347, 2021). "Taken together, these results indicate that NC inhibits the EMT process and glioma stem‐like properties via JAK2/STAT3 signaling pathway, suggesting that NC may be a potential anti‐glioma drug." (PMID 33788424, 2021). "Similarly, we observed that the phosphorylation of STAT3 (p-STAT3) was activated in the IL6 recombinant protein treatment in glioma cells." (PMID 33576874, 2021).
glioma (continued). "Based on these previous studies, STAT3 or miR-143a might be a molecular target in the regulation of HK2 expression in human glioma cells." (PMID 33922649, 2021). "Taken together, these results support that CYB561D2 up-regulation in gliomas could result in immunosuppression of T cells via STAT3." (PMID 34372858, 2021). "In addition, stress-induced phosphoprotein 1 (STIP1) secreted by TAMs induces proliferation of glioma cells in vitro, while IL-10 was shown to promote glioma cell proliferation via JAK2/STAT3 signaling in a glioma model." (PMID 34503065, 2021). "A previous study indicated that the inhibition of STAT3 could suppress the proliferation and the glycolysis of glioma cells." (PMID 34195079, 2021). "In the context of brain neoplasia, human CMV increases glioblastoma neurosphere proliferation and p-STAT3 levels, these findings suggested the existence of an association between CMV infection and STAT3-dependend modulation in glioma formation/progression, together with tumor suppressor mutations." (PMID 34163465, 2021). "Furthermore, we found that inhibition of STAT3 enhanced the upregulation of Bax and downregulation of Bcl-2 in glioma cells treated with the combination of sorafenib and TMZ." (PMID 34277607, 2021). "In addition, elevated expression of miR-124 in glioma stem cells inhibited the expression of STAT3 and reversed the inhibitory effect of glioma stem cells on the proliferation of T cells and the induction of Treg." (PMID 34084160, 2021). "In vitro glioma stem cell maintenance was attributed to TLR-9 dependent STAT3 regulation." (PMID 34439380, 2021). "Thus, our results support that CYB561D2 plays an oncogenic role through activating STAT3 in gliomas." (PMID 34372858, 2021). "Our findings also show that IL-6 and miR-155-3p may be novel biomarkers for diagnosing glioma and that treatment targeting autophagy and the STAT3 pathway may impair the immunosuppressive tumor microenvironment and participate in antitumor immunotherapy." (PMID 33828078, 2021). "In addition, we provide evidence that STAT1 directly binds to SH2B3 promoter and activates its expression in the transcriptional level, which in turn activates STAT3, thereby facilitating glioma progression." (PMID 33937225, 2021). "To understand the mode of action by which STAT3 degrader SD‐36 induce apoptosis in glioma cells, we assessed the effects of SD‐36 compared to Stattic on the modulation of multiple proteins related to STAT3 signalling and apoptosis primarily in U87 and U251 cell lines." (PMID 34291563, 2021). "Furthermore, the intensity of p-STAT3 in monocytes is another independent prognostic factor capable to discriminate gliomas versus HDs." (PMID 35069595, 2021). "The high expression and activation of STAT3 play an important role in gliomas." (PMID 34425834, 2021). "However, recent studies have also shown that the role of STAT3 in glioma is correlated to a degree with genetic alterations." (PMID 34276757, 2021). "As an effective JAK2/STAT3 inhibitor, NC represents a promising agent for the treatment of glioma." (PMID 33788424, 2021). "Moreover, IL-6 also increased cell proliferation, migration and invasion by activating JAK2/STAT3 signaling pathway in human glioma cells." (PMID 34165442, 2021). "Of note, arginase activity at neutral pH and intensity of activated STAT3 hold potential to discriminate between the different glioma grading and could also be used to monitor in glioma patients transition from low to high grade." (PMID 35069595, 2021). "In summary, our study revealed that UBE2D3 could promote the ubiquitination of SHP-2, which activated STAT3 pathway and promoted glioma proliferation as well as glycolysis." (PMID 34195079, 2021). "STAT3 also plays a significant role in the resistance to radiotherapy and chemotherapy of glioma." (PMID 34425834, 2021). "The inhibition of STAT3 could suppress the growth of glioma stem cells effectively combined with radiotherapy." (PMID 34195079, 2021).